BRAF (B-Raf proto-oncogene, serine/threonine kinase)
Diseases named in the same sentence as BRAF in open-access papers (continued):
Sharing a sentence is not in itself a finding about the gene and the disease.
metastatic melanoma (continued). "The developments of targeted therapies (TTs) directed at the oncogene BRAF and its downstream mediator MEK, and immune checkpoint inhibitors (ICI), have revolutionized the treatment of metastatic melanoma, improving patient outcomes." (PMID 36967556, 2023). "It was first approved for the treatment of metastatic melanoma that is refractory to CTLA4 and BRAF inhibitors." (PMID 36765809, 2023). "In a subsequent dose expansion phase of the study, the safety and preliminary antitumor activity of tovorafenib were further evaluated in cohorts of patients with BRAF-mutant, NRAS-mutant and BRAF/NRAS wild-type metastatic melanoma." (PMID 37219686, 2023). "The emergence of immune checkpoint inhibitors (ICI) and BRAF and MEK inhibitors has transformed the therapy of patients with metastatic melanoma over the last decade." (PMID 36006646, 2022). "Recommended management of common side effects with combination BRAF and MEK inhibition has been described in metastatic melanoma and are being used in the adjuvant setting as well." (PMID 36212431, 2022). "In addition, dabrafenib plus trametinib, compared with vemurafenib monotherapy, also significantly improved the overall survival in previously untreated patients with metastatic melanoma with BRAF V600E or V600K mutations and without increased overall toxicity." (PMID 36551302, 2022). "There is strong evidence for the beneficial clinical effects that BRAF and MEK inhibitors have in metastatic melanoma, increasing tumor immunogenicity, but the onset of resistance mechanisms makes them a temporary solution in many cases." (PMID 36358912, 2022). "Thus, depending on the class of kinase activation, MEKi currently remains an important therapeutic option for metastatic melanoma patients with an activating non-V600 BRAF mutation who have failed or are not eligible for immune checkpoint inhibitors in the first line." (PMID 35380338, 2022). "Several oncogenic BRAF-targeting inhibitors have been approved by the US FDA, including vemurafenib and dabrafenib, for the clinical treatment of metastatic melanoma." (PMID 35785205, 2022). "FDA-approved BRAF and MEK small molecule inhibitors have demonstrated some level of efficacy in patients with metastatic melanomas." (PMID 35899070, 2022). "The introduction of BRAF and MEK inhibitors profoundly impacts the treatment paradigm of patients with metastatic melanoma." (PMID 36579260, 2022). "By a poorly understood event, the combination of BRAF inhibitors and pan-HDAC inhibitors provides clinical benefits to metastatic melanoma patients." (PMID 36358912, 2022). "In this retrospective, real-world analysis, we analyzed the role of sequential treatment with BRAF/MEK inhibitors and CPI in 135 BRAF-mutant, metastatic melanoma patients." (PMID 35565212, 2022). "The combination of targeted therapy with BRAF/MEK inhibitors is being applied routinely in the clinic, significantly improving the response rates of patients with BRAF-mutant metastatic melanoma." (PMID 34123788, 2021). "PD-L1 regulation depends on the Janus kinase/signal transducer and activator of transcription (JAK/STAT) pathways controlled by MAPK pathways, and its expression is increased in BRAF and MEK inhibitor-resistant metastatic melanomas." (PMID 34769348, 2021). "The combination of BRAF and MEK inhibitors has become the standard treatment for metastatic melanoma." (PMID 35145907, 2021). "Targeted therapy, with BRAF and MEK inhibitors, and immunotherapy revolutionized the treatment of metastatic melanoma but there is still a considerable percentage of patients with primary or acquired resistance to these therapies." (PMID 33503876, 2021). "Next, we applied the BDA BRAF assay and comparative analyses to 12 FFPE SLNB or CLND samples from seven metastatic melanoma patients (patient 1–7)." (PMID 33907234, 2021).
metastatic melanoma (continued). "Furthermore, it is worth considering that the therapeutic landscape of metastatic melanoma has been also improved by the availability of target therapy based on the combination of BRAF and MEK inhibitors in approximately 50% of patients carrying mutations in the amino acid V600 of the BRAF oncogene." (PMID 33816298, 2021). "In fact, BRAF + MEK inhibitor combinations have been FDA-approved standard of care for late stage, unresectable or metastatic melanoma." (PMID 34461089, 2021). "The advent of BRAF inhibitor therapy, later in combination with MEK inhibition, revolutionized the treatment of metastatic melanoma." (PMID 33799709, 2021). "The phase 3 IMspire 150 trial (NCT02908672) combined atezolizumab, an anti-PD-L1 monoclonal antibody, with the BRAF/MEK inhibitor combination vemurafenib and cobimetinib in patients with BRAFV600-mutant metastatic melanoma." (PMID 33804800, 2021). "Following the establishment of efficacy of BRAF inhibition in metastatic melanoma, overall survival and response with the combination of BRAF with MEK inhibition was found to be superior compared to BRAF monotherapy." (PMID 34830796, 2021). "Based on positive clinical studies, vemurafenib was the first BRAF inhibitor to be approved by the Food and Drug Administration (FDA) as single‐agent therapy for metastatic melanoma." (PMID 33982883, 2021). "BRAF and MEK inhibitor (BRAFi/MEKi) combinations are currently the standard treatment for patients with BRAFV600 mutant metastatic melanoma." (PMID 34769379, 2021). "Dabrafenib (BRAF inhibitor) and trametinib (MEK inhibitor) target the mitogen-activated protein kinase pathway and have been used in combination for metastatic melanoma." (PMID 34884176, 2021). "Our previous study underscored the importance of signaling network rewiring in the acquisition of drug resistance to combined BRAF and MEK inhibitors in metastatic melanoma." (PMID 34304249, 2021). "To date, three different targeted therapies against BRAF and MEK have been approved for the treatment of advanced unresectable/metastatic melanoma, namely, vemurafenib plus cobimetinib, dabrafenib plus trametinib, and encorafenib plus binimetinib." (PMID 34073463, 2021). "Vemurafenib affects the transduction of RAF signal pathway in BRAF mutant cells by affecting the dimerization of RAF, which plays an important role in the treatment of metastatic melanoma." (PMID 35145907, 2021). "The use of novel immunotherapies, especially immune checkpoint inhibitors including CTLA-4, PD-1 and others, as well as targeted BRAF and MEK inhibitors have significantly improved outcomes for many patients with metastatic melanoma." (PMID 32894202, 2020). "The triple combination of atezolizumab, vemurafenib (BRAF V600E inhibitor), and cobimetnib (MEK inhibitor) was approved by the FDA as a first line therapy for BRAF V600 unresectable or metastatic melanoma." (PMID 33256089, 2020). "The introduction of targeted therapies whit BRAF and MEK inhibitors have changed the treatment of stage IV metastatic melanoma." (PMID 32575838, 2020). "The introduction of BRAF-targeted and ICI therapy for patients with metastatic melanoma has led to an increase in OS." (PMID 32367253, 2020). "Combining BRAF and MEK inhibitors has improved the average progression-free survival of metastatic melanoma from 5.8 to 9.4 months but many patients still suffer from resistance to combination therapy." (PMID 32411231, 2020). "In recent years the introduction of target therapies with BRAF and MEK inhibitors (MAPKi) and of immunotherapy with anti-CTLA-4 and anti-PD-1 monoclonal antibodies have dramatically improved survival of metastatic melanoma patients." (PMID 31557826, 2019). "An autopsy cohort of 50 patients with BRAF- and NRAS-mutant cutaneous metastatic melanomas including 139 visceral metastases was analysed for mutant allele fractions (MAF), determined by pyrosequencing and corrected for tumor/normal ratio." (PMID 31391014, 2019).
metastatic melanoma (continued). "In our studies, we investigated the antitumor activity of BRAF, MEK and CDK4/6 inhibitors in combination using both treatment responsive and drug-resistant BRAFV600E-mutant metastatic melanoma PDTXs." (PMID 29541385, 2018). "BRAF and MEK inhibitors have significantly changed the prognosis of metastatic melanoma, increasing the period of survival by months." (PMID 28640105, 2017). "BRAF and MEK inhibitors have significantly improved the prognosis of metastatic melanoma, by inhibiting both the mitogen-activated protein kinase (MAP-kinase) pathway." (PMID 28640105, 2017). "Starting enrollment in November 2008, the recruitment rate decreased significantly during 2011 due to the introduction of BRAF/MEK pathway inhibitors and immune checkpoint blockers for the treatment of advanced metastatic melanoma." (PMID 29100289, 2017). "New targeted treatment modalities, including BRAF and MEK inhibitors as well as immune checkpoint inhibitors, have revolutionized the treatment of metastatic melanoma patients in the last decade." (PMID 28374234, 2017). "Genetic alterations in BRAF, NRAS and NF1 that activate the ERK cascade, account for over 80% of metastatic melanomas." (PMID 29180761, 2017). "The MAPK kinase (MEK) is downstream of BRAF in the MAPK pathway, and pharmacological inhibition of both BRAF and MEK have shown major advancements in the treatment of metastatic melanoma." (PMID 28918496, 2017). "Similar results were observed in patients with metastatic melanoma treated with pembrolizumab, a highly selective inhibitor of PD1, also approved for metastatic melanoma patients who progressed after ipilimumab or BRAF inhibitors treatment if appropriated." (PMID 29202855, 2017). "Recent progress in systemic treatments, with checkpoint inhibitors and targeted therapies blocking BRAF and MEK, has redefined the standard of care of advanced unresectable and metastatic melanoma." (PMID 29214089, 2017). "After failure of immune checkpoint inhibitors or in patients progressing rapidly after BRAF and MEK inhibitors, chemotherapies, such as carboplatin and paclitaxel (CP), are still used to treat rapidly growing metastatic melanoma." (PMID 29157311, 2017). "Our results show a significant reduction in cell viability 5 days after transfection of the metastatic melanoma cell lines WM266-4, A2058, 1205Lu (all BRAF V600-mutant) and SK-MEL-2 (BRAF WT, NRASQ61K) with miR-7-5p." (PMID 27203220, 2016). "Despite great breakthrough of targeted therapies (e.g., BRAF inhibitors and MEK inhibitors) have revolutionized the treatment strategies for metastatic melanoma, durable clinical responses remain elusive." (PMID 27448964, 2016). "In this case we decided to continue Dabrafenib, preferring to treat the metastatic melanoma more than shifting to adjuvant chemotherapy because of RAS and BRAF-WT gastric cancer." (PMID 26981153, 2016). "BRAF and MEK are component of the MAPK/ERK pathway and inhibitors of these proteins have significantly improved the outcome of metastatic melanoma." (PMID 26481107, 2015). "Based on our results in the SM1 model, we provide preclinical support for the therapeutic combination of BRAF and CSF-1R inhibition currently being tested in patients with BRAFV600 mutant metastatic melanoma (trial NCT01826448)." (PMID 25939769, 2015). "Alternative strategies to target the BRAF signalling are also been tested including MEK inhibitors, and both BRAF and MEK inhibitors are now approved as single agent therapies for metastatic melanoma." (PMID 26201960, 2015). "Several recent randomized clinical trials have preliminarily demonstrated that initial targeted therapy with combined BRAF and MEK inhibition is more effective in metastatic melanoma (MM) than single agent." (PMID 26143635, 2015). "Combination of BRAF and MEK inhibitors has been even proposed as a new targeted-therapy standard of care for BRAFV600-positive metastatic melanomas." (PMID 26322273, 2015).
metastatic melanoma (continued). "The anti-invasive activity of fisetin occurred through inhibition of BRAF-MEK-ERK (MAPK) and NFκB signaling pathways, which are aberrantly activated in a majority of metastatic melanomas." (PMID 24466036, 2014). "BRAF inhibitors, used as single agents or in combination with MEK inhibitors, are active in most patients with metastatic melanoma, but the extent of response and time to progression are variable between patients, and complete responses are uncommon." (PMID 24400126, 2014). "In patients with BRAFV600 mutant metastatic melanoma, MART-1 expression was upregulated in metastatic tumors after treatment with BRAF inhibition." (PMID 24194739, 2013). "Consequently, more selective BRAF inhibitors were subsequently tested in clinical trials, which in case of vemurafenib (also known as PLX 4032) and GSK2118436 have demonstrated unprecedented clinical results in metastatic malignant melanoma harboring BRAF mutation." (PMID 22007305, 2011). "In order to explore the effect of irisin on metastatic melanoma (MM) cell viability, we treated the MM cell lines HBLwt/wt, LND1wt/wt, Hmel1V600K/wt and M3V600E/V600E, characterized by the oncogenic activation of BRAF, with different concentrations of r-irisin, for 24 h and 48 h." (PMID 39859367, 2025). "The unique pharmacokinetics of BRAF and MEK inhibitors make patients vulnerable to drug–drug interactions (DDIs), which may compromise treatment efficacy in metastatic melanoma." (PMID 40451782, 2025). "Vemurafenib was the first BRAF inhibitor to have FDA approval on 17 August 2011 for unresectable and metastatic melanoma, followed by dabrafenib on 29 May 2013." (PMID 38203795, 2024). "It has also been demonstrated that levels of mutant BRAF and NRAS ctDNA concentrations in patients with metastatic melanoma correlated with decreased metabolic activity monitored by fluorodeoxyglucose positron emission tomography (FDG-PET) in response to therapeutic interventions." (PMID 39156972, 2024). "P62, an autophagy-degrading factor, is overexpressed in malignant and metastatic melanomas regardless of BRAF/NRAS mutant status." (PMID 36747120, 2023). "Nivolumab was FDA approved on the 22nd of December 2014 after proving effective for the treatment of patients with unresectable or metastatic melanoma who no longer responded to ipilimumab and B-Raf proto-oncogene (BRAF) inhibitors." (PMID 37373192, 2023). "Furthermore, a phase III clinical trial in metastatic melanomas showed a better progression free survival and overall survival in patients who received a combined therapy with MEK and BRAF inhibitors than in those treated with single-agent therapy." (PMID 36979325, 2023). "Pharmacological inhibition of the MAPK pathway members BRAF and MEK or monoclonal antibodies against immune checkpoint markers CTLA-4 and PD-1 have provided metastatic melanoma patients with previously unattainable opportunities for meaningful and durable responses." (PMID 36497341, 2022). "Nonetheless, in a monocentric study with 260 patients with metastatic melanoma treated with BRAF inhibitors, none of them developed BP." (PMID 35936009, 2022). "Reschke suggests that acquired resistance to BRAF and MEK inhibitors in metastatic melanoma might be reversible under “drug-free” conditions." (PMID 35814395, 2022). "A landmark phase III randomized control trial compared Vemurafenib (RO5185426) with dacarbazine in patients with BRAF V600E mutant metastatic melanoma who had not previously received any treatment." (PMID 36699049, 2022). "The biopsy analysis of metastatic melanoma patients showed that selectively inhibiting BRAF with PLX4720 or GSK2118436 induced abundant CD8+ T cells in tumors, which provided powerful support for combining BRAF inhibitors with immunotherapy." (PMID 36189283, 2022). "Combination BRAF (vemurafenib, dabrafenib, or encorafenib) plus MEK (trametinib, cobimetinib, or binimetinib) inhibitor therapy is now widely used in the treatment of metastatic melanoma." (PMID 36579260, 2022).
metastatic melanoma (continued). "Moreover, the most recently explored option is the triple combination therapy of BRAF and MEK inhibitors with immunotherapy in patients with BRAF(V600E) metastatic melanoma." (PMID 33672955, 2021). "However, median PFS was only 3.5 months in BRAF-mutant CRC, while it was approximately 9.5 months in BRAF mutant metastatic melanoma." (PMID 34063682, 2021). "The same effect was reported by several other studies about metastatic melanoma patients who did not respond to the targeted therapy due to BRAF amplification." (PMID 34885093, 2021). "For example, various studies have shown that targeting pathways involved in melanoma tumor growth and survival including BRAF and MAPK pathways with specific inhibitors such as vemurafenib and trametinib, respectively, contribute to enhanced overall survival of metastatic melanoma patients." (PMID 34207884, 2021). "For cutaneous melanoma, BRAF mutation has been a point of interest for potential targeted therapy in metastatic melanoma; however, there are only a few publications consisting of single reports regarding BRAF with or without MEK inhibition in CM." (PMID 33389937, 2020). "Since early studies assessing BRAF inhibitors as monotherapy have shown limited activity, recent trials have been focused on the dual inhibition of BRAF and MEK, trying to translate previous evidence for other malignancies, such as metastatic melanoma, in this setting." (PMID 33158162, 2020). "Starting from the rationale that BRAF and MEK inhibitors have the ability to increase T cell responses through a variety of immunological changes, researchers combined BRAF/MEK inhibitors and anti-PD1 antibodies to achieve a synergistic effect in the treatment of metastatic melanoma." (PMID 31979325, 2020). "Since MEK acts downstream to BRAF in the MAPK pathway, a combination of BRAF and MEK inhibitors such as vemurafenib, dabrafenib, trametinib and cobimetinib have improved the effect of treatment of patients with advanced and metastatic melanoma." (PMID 31820036, 2020). "Dual therapy with nivolumab plus ipilimumab seems to achieve higher response rates and prolong survival more than nivolumab monotherapy in metastatic melanoma patients, regardless of the BRAF status." (PMID 31979325, 2020). "Since resistance is a major impediment to long-term survival for patients with metastatic melanoma, and ABL kinases are activated by ERK pathway components (BRAF, ERK) and activate ERK16, we tested whether ABL1/2 drive BRAFi or BRAFi/MEKi resistance." (PMID 33122628, 2020). "The combination of a BRAF inhibitor (dabrafenib) and a MEK inhibitor (trametinib) increases the expression of KIT, a tumor suppressor, and also induces alterations in CCND1, RB1, and MET in patients with BRAFV600E metastatic melanoma." (PMID 32626712, 2020). "Monotherapy with BRAF inhibitors and combined therapy with BRAF inhibitors and MEK inhibitors have been approved by the Food and Drug Administration in the United States of America and other countries worldwide for targeted therapy of metastatic melanoma." (PMID 31277584, 2019). "The expression levels of 90 lncRNAs that were potentially connected with the cancer process was evaluated in 58 BRAF-mutant metastatic melanoma patients and 15 healthy donors (controls) without any histories of cancer or chronic diseases." (PMID 31231466, 2019). "We performed a nonrandomized, open-label phase II study, where 183 metastatic melanoma patients received binimetinib 45 mg / 60 mg twice-daily (BRAF arms), or binimetinib 45 mg twice-daily (NRAS arm)." (PMID 30956763, 2019). "Surprisingly, the published results for monitoring BRAF or NRAS mutant metastatic melanoma have not been adopted in routine clinical oncology." (PMID 30546839, 2018). "Sequential therapy involving any number of immunotherapeutic agents is not an uncommon approach in the treatment of patients with metastatic malignant melanoma, regardless of BRAF status, once their disease progresses." (PMID 29898784, 2018).